FOXN2 (forkhead box N2)
Description:
Binds to the purine-rich region in HTLV-I LTR.
Synonyms: HTLF
Tractability: PROTAC: ubiquitination databases record sites on it.
Gene: Protein-coding gene on chromosome 2 (48,314,331 to 48,379,295, forward strand). Ensembl gene ENSG00000170802.
Subcellular location: Nucleus
Subcellular location (Human Protein Atlas): Nucleoplasm; Vesicles
Gene Ontology:
Molecular function: protein binding; sequence-specific double-stranded DNA binding; cis-regulatory region sequence-specific DNA binding; DNA-binding transcription factor activity; DNA-binding transcription factor activity, RNA polymerase II-specific; sequence-specific DNA binding
Biological process: regulation of DNA-templated transcription; regulation of transcription by RNA polymerase II
Cellular component: nucleoplasm; chromatin; nucleus
Genetic constraint (gnomAD): Loss-of-function variants: 16 observed, 33.08 expected, observed/expected ratio (o/e) 0.48, 90% interval 0.33 to 0.74. The upper end of that interval is the gene's LOEUF score, 0.74, which puts it in group 3 of 6, group 1 being the genes least tolerant of losing a copy. Missense variants: 543 observed, 495.25 expected, observed/expected ratio (o/e) 1.1, 90% interval 1.02 to 1.18. Synonymous variants: 183 observed, 175.48 expected, observed/expected ratio (o/e) 1.04, 90% interval 0.92 to 1.18.
Homologues: Orthologues: chimpanzee FOXN2 (100% identical), macaque FOXN2 (99% identical), dog FOXN2 (94% identical), rabbit FOXN2 (94% identical), pig FOXN2 (93% identical), guinea pig FOXN2 (90% identical), mouse Foxn2 (84% identical), rat Foxn2 (84% identical), tropical clawed frog foxn2 (72% identical), zebrafish foxn2b (44% identical), zebrafish FOXN2 (37% identical). Paralogues in human: FOXN3 (46% identical), FOXN4 (23% identical).
Diseases named in the same sentence as FOXN2 in open-access papers:
FOXN2 is named in the same sentence as 23 diseases in open-access papers, as found by Europe PMC text mining. Sharing a sentence is not in itself a finding about the gene and the disease. The quoted sentences say what the papers report.
lung carcinoma (8 papers, 2020 to 2023). "FOXN2 is widely expressed in many organs and tissues in humans and has a critical role in various malignancies, such as breast cancer, lung cancer, cervical cancer, and HCC." (PMID 37277714, 2023). "The degradation of FOXN2 promotes tumorigenesis and radioresistance in lung cancer cells, but our results identified FOXN2 as a possible oncogene in PAAD." (PMID 36622275, 2023). "The ribosomal protein S6 kinase alpha-3 (RSK2)-mediated degradation of FOXN2 promotes tumorigenesis and radioresistance in lung cancer cells." (PMID 34830778, 2021). "Contradicting our results, previous studies have shown that FOXN2 may serve as a tumor suppressor in breast cancer, lung cancer, and human oral cancer." (PMID 36622275, 2023). "In addition, it has been shown that low FOXN2 expression is correlated with poor prognosis in adult glioblastoma multiforme and poor survival in lung cancer patients." (PMID 35008435, 2021). "A recent study showed that FOXN2 could suppress the proliferation of lung cancer cells." (PMID 32046688, 2020). "In CRUK0046, we found several genes (FOXN2,GAS1, etc.)in the stem of the phylogeny that are of suggestedimportance for lung cancer initiation, resistance, and metastasis." (PMID 34343239, 2021). "Moreover, FOXN2 degradation mediated by β-Trcp and RSK2 can facilitate lung cancer occurrence and radioresistance." (PMID 37277714, 2023).
breast carcinoma (4 papers, 2022 to 2023). "A previous study reported that the human ortholog FOXN2 gene was significantly downregulated in breast cancer tissues and cell lines." (PMID 37958330, 2023). "Further in vitro experiments confirmed that ectopic expression of FOXN2 suppressed the proliferation of breast cancer cells, and the inhibition of FOXN2 promoted tumor growth, strongly supporting the tumor suppressor roles." (PMID 37958330, 2023). "FOXN2 knockdown dramatically promotes breast cancer cell proliferation, migration, and invasion, and represses epithelial–mesenchymal transition." (PMID 37277714, 2023). "Ye and Duan found that FOXN2 is downregulated in breast cancer and modulates invasion, migration, and epithelial-mesenchymal transition via regulation of SLUG." (PMID 36407085, 2022). "For example, low FOXN2 expression predicts poor prognosis in breast cancer." (PMID 37277714, 2023).
cervical cancer (3 papers, 2022 to 2023). A primary or metastatic malignant neoplasm involving the cervix. "FOXN2 plays an important role in the development of several tumors, including breast and cervical cancers." (PMID 35602603, 2022).
Alzheimer disease (1 paper, 2023). A progressive, neurodegenerative disease characterized by loss of function and death of nerve cells in several areas of the brain leading to loss of cognitive function such as memory and language. "While FOXN2 has not been specifically identified in neurodegenerative disease or cognitive functional research, perturbations in these molecular pathways have been identified in Alzheimer’s disease as well as cancer." (PMID 37296840, 2023).
liver cancer (1 paper, 2022). An epithelial or non-epithelial malignant neoplasm that arises from the liver. "Furthermore, 1000 lasso analysis also identified five genes: ADH4, AKR1B10, CEBPZOS, ENO1, and FOXN2, as the most stable prognosis-related genes associated with energy metabolism in liver cancer." (PMID 35602603, 2022). "FOXN2 has been shown to be associated with tumor cell proliferation and invasion in liver cancer." (PMID 35602603, 2022). "Based on the marker genes of this cluster and TCGA database data, the five most stable key genes (ADH4, AKR1B10, CEBPZOS, ENO1, and FOXN2) were identified as energy metabolism-related genes in liver cancer." (PMID 35602603, 2022).
Obesity (1 paper, 2023). Accumulation of substantial excess body fat. "The aryl hydrocarbon receptor nuclear translocator like (ARNTL), a gene that regulates the circadian release of PUFAs and modulates feeding behavior in mice, alongside with forkhead box N2 (FOXN2), are associated with obesity." (PMID 37141193, 2023).
osteoarthritis (1 paper, 2025). A noninflammatory degenerative joint disease occurring chiefly in older persons, characterized by degeneration of the articular cartilage, hypertrophy of bone at the margins and changes in the synovial membrane. "FGF18 is linked to osteoarthritis (OA) progression, but its relationship with FOXN2 and its roles in post-traumatic osteoarthritis (PTOA) remain unclear." (PMID 41323462, 2025).
T-cell leukemia (1 paper, 2021). A malignant disease of the T-lymphocytes in the bone marrow, thymus, and/or blood. "A recent study indicated that FOXN2 may act as a tumor suppressor in T-cell leukemia." (PMID 35008435, 2021).
tumor (8 papers, 2020 to 2023). "miR-188 and FOXN2 mRNA expression levels in mouse tumor samples (n = 6) were also determined." (PMID 37277714, 2023). "The tumor-inhibitory role of miR-188 is probably mediated by the targeting of FOXN2." (PMID 37277714, 2023). "This raises the question what particular mi-188-5p-targeted FOXN2 can regulate tumor development." (PMID 35008435, 2021). "FOXN2 has been found to play key roles in various types of human cancers as a tumor suppressor." (PMID 35008435, 2021). "Overexpression of mir-188-5p inhibited the expression of forkhead box N2 (FOXN2), a tumor suppressor gene." (PMID 35008435, 2021).
cancer (6 papers, 2021 to 2024). A tumor composed of atypical neoplastic, often pleomorphic cells that invade other tissues. "The closest gene to this locus is forkhead box N2 (FOXN2), which is ubiquitously expressed and has been shown to suppress cancer proliferation and invasion." (PMID 37296840, 2023). "FOXN2 acts as atumor suppressor in multiple cancers, including breast, lung and liver 42–44." (PMID 39070636, 2024). "By integrating patterns of FOX genes expression with anticancer drugs sensitivity, we speculated that six FOX genes, including FOXO3, FOXO1, FOXN3, FOXK2, FOXN2, and FOXJ3, might be important for the development and treatment of a wide range of cancers." (PMID 36292640, 2022). "Our findings suggest that miR-188-5p exerts significant cancer-promoting effects in HOXC6-mediated cancer progression by inhibiting FOXN2 expression; thus, miR-188-5p might be a potential prognostic marker and therapeutic target for HOXC6-overexpressing cancers." (PMID 35008435, 2021).
infection (2 papers, 2023 to 2024). The state of being infected such as from the introduction of a foreign agent such as serum, vaccine, antigenic substance or organism. "MiR-188 was found to be upregulated, whereas FOXN2 mRNA expression was reduced in LM3-LV-miR-188-inoculated mice relative to levels in mice in the LM3 infection group." (PMID 37277714, 2023).
endocrine disease (1 paper, 2022). "Notably, FOXN2 had genetic variants statistically associated with the risk of both AD and SCZ, and NOTCH2 displayed genetic variants that are statistically associated with the risk of both endocrine disease and kidney disease." (PMID 36204511, 2022).
FOXN2 also shares sentences with these, for which no sentence is quoted: hepatocellular carcinoma (2 papers); acute lymphoblastic leukemia (1); adenocarcinoma (1); endometriosis (1); glioblastoma multiforme (1); kidney disease (1); leukemia (1); nervous system tumors (1); neurodegenerative disease (1); oral cancer (1); T-cell acute lymphoblastic leukemia (1).